DDIT4 (DNA damage inducible transcript 4)
Diseases named in the same sentence as DDIT4 in open-access papers (continued):
Sharing a sentence is not in itself a finding about the gene and the disease.
pancreatic cancer (10 papers, 2020 to 2025). "Both results revealed that DDIT4 can be considered a risk factor for the progression of pancreatic tumor and plays an oncogenic role in the pancreas." (PMID 37938616, 2023). "ROC curves, and the AUC of the expression level of DDIT4 protein (nuclear, cytoplasmic, and membranous) were performed to explore the diagnostic value of the marker in discriminating pancreatic tumor from adjacent normal tissues." (PMID 37938616, 2023). "In order to further clarify the correlation between 3′-UTR mutation and DDIT4 expression level, we performed IHC in pancreatic tumor tissue including several combinations of two types of genetic mutations." (PMID 34007269, 2021). "In the future, we may monitor the mutation level of DDIT4 in tissues through detecting the mutation level of DDIT4 in blood samples of pancreatic cancer patients and then realize effective assessments of chemotherapy resistance and poor prognosis." (PMID 34007269, 2021). "In this study, we found a gene mutation in the 3′-UTR region of DDIT4, which may be associated with DDIT4 expression and tumor autophagy in pancreatic cancer tissues, and the further mechanistic research requires more work." (PMID 34007269, 2021). "In summary, DDIT4 has gene mutations in 3′-UTR in pancreatic cancer tissues, which may be related to the binding site of microRNA and affected the expression level and localization of DDIT4." (PMID 34007269, 2021). "The UTR mutation of DDIT4 is involved in autophagy of pancreatic cancer cells by regulating the expression of DDIT4, and it may be a potential biomarker for chemotherapy resistance and poor prognosis." (PMID 34007269, 2021). "The DDIT4 gene mutation in pancreatic cancer cells leads to a base-point mutation in DDIT4 3′-UTR, and it may affect protein localization which may be involved in its biological function." (PMID 34007269, 2021). "In this study, we found mutation in the 3′-UTR region of DDIT4, which may be associated with DDIT4 expression and tumor autophagy in pancreatic cancer tissues." (PMID 34007269, 2021). "In addition, we used IHC to detect the expression level of DDIT4 in patients with pancreatic cancer in different types of gene mutation." (PMID 34007269, 2021). "In order to further discuss the clinical value of DDIT4 gene mutation, immunofluorescence suggested that the expression of DDIT4 colocated with LC3; thus, we speculated that DDIT4 mutation may be involved in autophagy in pancreatic cancer cell." (PMID 34007269, 2021). "We speculated that DDIT4 gene mutation may be involved in pancreatic cancer cell adapted to antitumor therapy and harsh microenvironment." (PMID 34007269, 2021). "DDIT4 gene mutations may result in the antitumor resistance through abnormal protein localization in the pancreatic tumor cells." (PMID 34007269, 2021). "Conversely, the prognosis of patients with lung or pancreatic cancers harboring RAS mutations and DDIT4 deletion is poor." (PMID 37671155, 2023). "Of note, these data support the direct role of DDIT4 in pancreatic tumors, which can be used to diagnose the PT." (PMID 37938616, 2023). "This study is aimed at searching the possible genetic mutations and the value of novel gene mutation in the DNA damage-inducible transcript 4 (DDIT4) and signaling pathway in pancreatic cancer." (PMID 34007269, 2021). "The colocalization of DDIT4 and LC3 indicated that DDIT4 was highly expressed in pancreatic cancer tissues and its expression is involved in autophagy." (PMID 34007269, 2021). "Based on our experimental results and relevant literature, we summarized the relationship between DDIT4 3′-UTR mutation and pancreatic cancer." (PMID 34007269, 2021). "At the same time, we found a correlation between the expression level of DDIT4 and the type of gene mutation, and DDIT4 was colocated with LC3 obviously in pancreatic cancer." (PMID 34007269, 2021).
pancreatic cancer (continued). "Our results revealed that the expression levels of DDIT4 protein proved that the molecule may be considered the potential marker for diagnosis of pancreatic cancer patients with high sensitivity." (PMID 37938616, 2023). "However, further investigations should be conducted regarding the molecular mechanisms of DDIT4 in the progression of pancreatic tumor." (PMID 37938616, 2023). "Thus, this is the first study that evaluates the expression, prognostic, and diagnostic value of DDIT4 in both mRNA and protein levels in either PDAC or PNET forms of pancreatic tumor." (PMID 37938616, 2023). "Our results indicated that DDIT4 had a higher expression level in poor differentiated adenocarcinoma compared to other pancreatic cancer pathological styles including the moderately differentiated adenocarcinoma, highly differentiated adenocarcinoma, and false papilloma of pancreatic cancer." (PMID 34007269, 2021). "Combined with our results, microRNA may be closely related to DDIT4 function in pancreatic cancer." (PMID 34007269, 2021). "Interestingly, DDIT4 has been identified as a prognosis marker and highly expressed in pancreatic tumors, thus prompting the investigation into whether DDIT4 inhibition might be the triggering mechanism of action and thus serve as a predictive biomarker for CK21 sensitivity." (PMID 37877568, 2023). "BHLHE and DDIT4 were also found to be specific markers for HCC compared with other cancers such as head and neck cancers and pancreatic cancer." (PMID 34045534, 2021). "Furthermore, CU-DREAMX analysis demonstrated that BHLHE40 and DDIT4 of PBMCs were not increased in patients with head and neck cancers and pancreatic cancer." (PMID 34045534, 2021).
Parkinson disease (10 papers, 2014 to 2025). A progressive degenerative disorder of the central nervous system characterized by loss of dopamine producing neurons in the substantia nigra and the presence of Lewy bodies in the substantia nigra and locus coeruleus. "Most significantly, DDIT4 has been shown to change its levels in response to stress and to be enhanced in brains with age-related neurodegenerative conditions like Parkinson's disease." (PMID 30116473, 2018).
acute myeloid leukemia (9 papers, 2017 to 2025). Acute myeloid leukemia (AML) is a group of neoplasms arising from precursor cells committed to the myeloid cell-line differentiation. "DDIT4, also known as regulated in development and DNA damage response-1 (Redd1), is highly expressed and associated with a worse prognosis in acute myeloid leukemia and solid tumors." (PMID 37880985, 2024). "More importantly, analysis of publicly available transcriptional data from adult acute myeloid leukemia (AML) patients revealed that elevated DDIT4 expression correlates with poor prognosis." (PMID 40621878, 2025).
Alzheimer disease (9 papers, 2013 to 2025). A progressive, neurodegenerative disease characterized by loss of function and death of nerve cells in several areas of the brain leading to loss of cognitive function such as memory and language. "Ddit4 has also been implicated in Alzheimer’s disease and is therefore highly relevant for memory processes." (PMID 23927422, 2013). "In the context of Alzheimer’s disease (AD), the coding gene for RTP801, DDIT4, is responsive to Aβ and modulates its cytotoxicity in vitro." (PMID 34131105, 2021). "Moreover, DDIT4, a REDD1 gene, is a gene responding to amyloid β (Aβ), a pathological hallmark of Alzheimer’s disease." (PMID 33322202, 2020).
emphysema (8 papers, 2016 to 2024). "In cigarette smoke-induced pulmonary injury and emphysema, DDIT4 is necessary and sufficient for nuclear factor-kappaB (NF-kappaB) activation, and promoted alveolar inflammation, oxidative stress and apoptosis in alveolar septal cells." (PMID 29976242, 2018).
leukemia (8 papers, 2007 to 2025). A malignant (clonal) hematologic disorder, involving hematopoietic stem cells and characterized by the presence of primitive or atypical myeloid or lymphoid cells in the bone marrow and the blood. "It was confirmed that re‐expression of Hoxa6 can partly rescue the leukemia initiation defect caused by Ddit4 deletion." (PMID 40621878, 2025). "To better understand the molecular mechanisms underlying the role of DDIT4 in self‐renewal of leukemia cells and leukemia initiation, we performed global gene expression profiling by RNA sequencing on AE9a‐Ddit4+/+ and AE9a‐Ddit4−/− leukemia cells." (PMID 40621878, 2025). "Here, we demonstrate that DDIT4 can be upregulated in the endosteal bone marrow region in the AE9a leukemia mouse, and Ddit4 deficiency suppresses AML initiation and leads to a defect in quiescence maintenance and self‐renewal of leukemia cells." (PMID 40621878, 2025). "Although the antiapoptotic effect of DDIT4 has been preliminarily demonstrated in leukemia cells, the underlying mechanisms of its role in stemness, including drug resistance, remain to be fully elucidated." (PMID 40621878, 2025). "The overall survival time in AML patients with high DDIT4 level (n = 57) was significantly shorter than that of those with low DDIT4 expression (n = 56) (P < 0.01), indicating that a higher DDIT4 level in leukemia cells is associated with worse prognosis." (PMID 40621878, 2025). "Ddit4 deletion resulted in a defect in AE9a‐induced leukemogenesis and caused downregulated Hoxa cluster gene expression, suggesting that decreased Hoxa cluster expression confers a leukemia initiation defect in AE9a‐Ddit4−/− cells." (PMID 40621878, 2025). "Survival analysis showed that the median survival time of AE9a‐induced leukemia was significantly prolonged by deletion of Ddit4." (PMID 40621878, 2025). "Herein, we investigated the potential role and mechanism of DDIT4, which is upregulated in leukemia cells in endosteal BM, in leukemogenesis and maintaining quiescence and self‐renewal of leukemia cells." (PMID 40621878, 2025). "Once a mouse transplanted with AE9a‐Ddit4+/+ leukemia cells showed a high circulating GFP+ cell count (defined as > 80% GFP+ cells in PB), all six recipient mice in each group (total 12 mice) were euthanized simultaneously." (PMID 40621878, 2025). "Following a rapid increase in GFP+ cells, AE9a‐Ddit4+/+ mice exhibited a more immature myeloid phenotype and subsequently progressed to leukemia." (PMID 40621878, 2025). "We next examined the role of DDIT4 in quiescence maintenance and self‐renewal of leukemia cells in vitro." (PMID 40621878, 2025). "Our study provides evidence for the critical role of DDIT4 in leukemia development and stemness maintenance of LSCs." (PMID 40621878, 2025). "In Ara‐C treated AE9a leukemia mice, Ddit4 expression in EBM leukemia cells was significantly higher than that in untreated mice." (PMID 40621878, 2025). "The leukemia initiating frequency in AE9a‐Ddit4−/− leukemic cells was 4.7‐fold lower than that in AE9a‐Ddit4+/+ leukemic cells (1/34965 versus 1/7388 cells, P = 0.0126)." (PMID 40621878, 2025). "The same numbers of AE9a‐Ddit4+/+ and AE9a‐ Ddit4−/− GFP+ leukemia cells were transplanted into sublethally irradiated recipients, respectively." (PMID 40621878, 2025). "AE9a leukemia mice were treated with Ara‐C for 3 days, and then, Ddit4 expression levels were determined in the EBM leukemia cells from Ara‐C treated and untreated mice." (PMID 40621878, 2025). "To elucidate the role of DDIT4 in the self‐renewal of leukemia cells, we further examined the effect of deletion of Ddit4 in AE9a‐induced leukemogenesis." (PMID 40621878, 2025). "As expected, six out of eight mice that received 10 000 AE9a‐Ddit4+/+GFP+ cells developed leukemia with a mortality of 75%, while the mortality of mice receiving 10 000 AE9a‐Ddit4−/− GFP+ leukemic cells was only 12.5%." (PMID 40621878, 2025).
leukemia (continued). "Mechanistically, DDIT4 upregulates the expression of HOXA gene cluster, and re‐expression of HOXA6 in DDIT4 knockout AE9a cells can rescue the impaired leukemia initiation." (PMID 40621878, 2025). "In summary, our findings demonstrate that DDIT4 plays a critical role in leukemia development, regulates leukemia cell self‐renewal, and contributes to chemoresistance." (PMID 40621878, 2025). "Among these genes, the DNA damage‐inducible transcript 4 (Ddit4) gene was significantly overexpressed in AE9a leukemia cells in the endosteal BM." (PMID 40621878, 2025). "Deletion of Ddit4 resulted in delayed AE9a‐induced leukemia development, indicating that DDIT4 is critical for leukemia development and the self‐renewal capacity of leukemia cells." (PMID 40621878, 2025). "In order to demonstrate the role of DDIT4 in leukemia cell stemness, we explored the function of DDIT4 in chemoresistance, quiescence, and self‐renewal of AE9a leukemia cells." (PMID 40621878, 2025). "The results demonstrate that DDIT4 plays a critical role in maintaining quiescence and chemoresistance in AE9a leukemia cells in vivo." (PMID 40621878, 2025). "We further validated DDIT4 expression levels in leukemia cells isolated from the endosteal BM and central BM." (PMID 40621878, 2025). "AE9a‐Ddit4−/− GFP+ leukemia cells were retrovirally transduced with Hoxa6‐RFP expressing construct (MSCV‐Hoxa6‐IRES‐RFP) or empty vector (MSCV‐IRES‐RFP)." (PMID 40621878, 2025). "Our data provide evidence that DDIT4 plays a critical role in leukemia cell stemness maintenance and leukemia initiation." (PMID 40621878, 2025). "It makes it more believable that in leukemia cells in vivo, DDIT4 can be induced by the endosteal niche and perform its function." (PMID 40621878, 2025). "To explore the role of DDIT4 in the immune infiltration of leukemia, we analyzed the relationship between the expression level of DDIT4 and the expression of 24 kinds of immune cells." (PMID 38507057, 2024). "To investigate the role of DDIT4 in AML, we used small interfering RNAs (siRNAs) to knock down DDIT4 in leukemia cell lines THP1 and NB4." (PMID 38507057, 2024). "Together, these results implicate both FAM83A and DDIT4 as mediators of leukemia suppression by lovastatin." (PMID 37016335, 2023). "ONC201/TIC10 caused apoptosis through ATF4 in lymphoma and leukemia cells and inhibited mTORC1 signaling through the upregulation of ATF4 and DDIT4." (PMID 37772709, 2023). "HSPCs derived from Ddit4+/+ and Ddit4−/− mice were used to establish AE9a‐induced leukemia models." (PMID 40621878, 2025). "The data indicate that the expression of DDIT4 could be induced and upregulated in AE9a leukemia cells located in the endosteal region." (PMID 40621878, 2025). "Mechanistically, the HOXA gene cluster mediates DDIT4's function in leukemia." (PMID 40621878, 2025). "In addition to its role in self‐renewal, we further investigated the involvement of DDIT4 in quiescence and chemotherapy resistance using AE9a‐Ddit4−/− and AE9a‐Ddit4+/+ leukemia cells isolated from the mice and analyzed ex vivo." (PMID 40621878, 2025). "Collectively, these results support the hypothesis that DDIT4 is essential for chemoresistance, quiescence, and self‐renewal of leukemia cells." (PMID 40621878, 2025). "These help to support the hypothesis that DDIT4 may be involved in the chemoresistance and stemness of leukemia cells." (PMID 40621878, 2025). "Analysis of the AML cohort from the public database demonstrates that patients with high DDIT4 expression have shorter survival times, implying that DDIT4 may be involved in the chemoresistance of leukemia cells." (PMID 40621878, 2025). "Mechanistically, HOXA cluster specifically mediate the leukemia‐promoting effects of DDIT4." (PMID 40621878, 2025). "However, after these leukemia cells were co‐cultured with osteoblast cells, AE9a/Ddit4+/+ cells exhibited a significant advantage in colony formation ability and had more cells in G0 phase." (PMID 40621878, 2025).
leukemia (continued). "To further confirm the effect of upregulated DDIT4 in AE9a leukemia cells by the endosteal region, we measured DDIT4 expression levels in AE9a cells co‐cultured with mouse OBC and BM MSC cells, as well as the mouse osteoblast cell line MC3T3‐E1 and MSC cell line OP9." (PMID 40621878, 2025). "Using an AE9a leukemia mouse model, we first determined whether Ddit4 high‐expressing cells could resist chemotherapy." (PMID 40621878, 2025). "The median level in the Ara‐C treated group was 1.9‐fold higher than that in the untreated group, which indicated that high Ddit4 expressing leukemia cells in EBM could be enriched by drug treatment." (PMID 40621878, 2025). "Cell cycle analysis revealed that in both cell lines, in DDIT4 overexpression cells, the ratio of cells in the G0 cell cycle phase was increased significantly, indicating that DDIT4 plays a role in maintaining quiescence in leukemia cells." (PMID 40621878, 2025). "To further assess whether DDIT4 is necessary for AML leukemia maintenance, we performed secondary transplantation." (PMID 40621878, 2025). "Furthermore, DDIT4 knockout markedly suppressed leukemia initiation, quiescence, chemoresistance, and self‐renewal of AE9a‐transformed leukemia cells in vivo." (PMID 40621878, 2025). "Here, we found that DDIT4 in leukemia cells could be upregulated in the endosteal niche and DDIT4 was critical for leukemia cells stemness maintenance." (PMID 40621878, 2025). "Furthermore, using AE9a‐Ddit4+/+ and AE9a‐Ddit4−/− leukemia cells from the primary transplanted mice, the LSC frequency and the role of DDIT4 in self‐renewal of leukemia cells were further identified via limiting dilution transplantation assay." (PMID 40621878, 2025). "FAM83A and DDIT4 expression was knocked-downed in leukemia cells via lentivirus-shRNA." (PMID 37016335, 2023). "Targeting, FAM83A and DDIT4 using small molecule drugs alone or in combination with lovastatin could be useful in treating leukemias and other cancers." (PMID 37016335, 2023). "Our findings demonstrate the critical role of DDIT4 in the stemness of AE9a leukemia cells and elucidate its underlying mechanism, suggesting that targeting DDIT4 may represent a promising therapeutic strategy for eliminating LSCs in AML1‐ETO leukemia." (PMID 40621878, 2025). "Furthermore, the knockdown of DDIT4 was shown to promote cell apoptosis in leukemia cell lines." (PMID 40621878, 2025). "Here, we demonstrate that DNA damage‐inducible transcript 4 (DDIT4) is induced in the hypoxic bone marrow niche and is essential for maintaining the stemness of AML1‐ETO9a leukemia cells." (PMID 40621878, 2025). "Here, we demonstrated that DNA damage‐inducible transcript 4 (DDIT4) can be induced in a hypoxic BM niche and is required for the quiescence and self‐renewal of AML1‐ETO9a (AE9a)‐transformed leukemia cells in vitro." (PMID 40621878, 2025). "Lovastatin inhibits leukemia cell survival and proliferation in part through suppression of the FAM83A/DDIT4/ERK1/2 pathway, mediated by the induction of the tumor suppressor gene KLF2, as well as cholesterol biosynthesis genes." (PMID 37016335, 2023). "Western blot analysis confirmed the complete lack of DDIT4 expression in AE9a‐Ddit4−/− leukemia cells." (PMID 40621878, 2025). "In our in vitro assay, it was found that compared with AE9a/Ddit4−/− cells, AE9a/Ddit4+/+ leukemia cells did not exhibit significant differences in colony formation and G0 cell cycle phase under the condition that the cells were cultured without osteoblast cells." (PMID 40621878, 2025). "Notably, DDIT4 overexpression significantly upregulated HOXA cluster gene expressions in both kasumi‐1 and KG‐1a cells, confirming DDIT4 can upregulate HOXA gene expressions in leukemia cells." (PMID 40621878, 2025).